FOXO3 (forkhead box O3)
Diseases named in the same sentence as FOXO3 in open-access papers (continued):
Sharing a sentence is not in itself a finding about the gene and the disease.
tumor (continued). "When SGK1 expressing cells are treated with PI3Kα and PDK1 inhibitors, both AKT and SGK1 are inhibited, inducing tumour regression as a result of FOXO3 activation and mTORC1 inhibition." (PMID 40263319, 2025). "In other studies, it has also been shown that the activation of the ERK/MAPK signaling pathway can lead to the activation of the transcription factors FOXO1 and FOXO3, which also function as tumor suppressors." (PMID 41462911, 2025). "GINS complex subunit 1 (GINS1) promotes EMT and tumor metastasis by favoring β-catenin signaling, while Forkhead box O3 (FOXO3a) reduces the binding of β-catenin to the T-cell factor (TCF) and inhibits β-catenin/TCF target gene expression." (PMID 41303618, 2025). "The FOXO3/CCL22 pathway mediates the recruitment of regulatory T cells (Tregs) into the tumor microenvironment by regulating the expression of the chemokine CCL22, thereby promoting tumor immune escape." (PMID 41231037, 2025). "ZnDHT NM has been demonstrated to efficaciously suppress the EMT and CSC stemness by blocking the Wnt signaling pathway and activating FoxO3, and more importantly, is able to selectively kill tumor cells through inducing both apoptosis and ferroptosis." (PMID 39967605, 2025). "Recent research highlights the potential of Foxo3 as a therapeutic target in cancer management, underscoring its role as a tumor suppressor." (PMID 39729481, 2024). "In tumor cells, which exhibit highly active glycolytic metabolism, elevated nuclear levels of FOXO3 were correlated with apoptosis and reduced cell survival." (PMID 39061940, 2024). "Forkhead box O3 (Foxo3), also known as Foxo3a and FKHR-L1, is recognized as a critical tumor suppressor." (PMID 39729481, 2024). "In this sense, the authors found research showing that, in addition to its function as a tumor suppressor, nuclear FOXO3 can also promote tumor cell survival." (PMID 38636197, 2024). "These analyses indicated an elevated FOXO3 expression in normal tissues, while it was reduced in tumor tissues." (PMID 37976368, 2024). "PTEN (Phosphatase and Tensin Homologue) suppresses AKT activation, preventing its nuclear translocation and further activating FOXO3 (Forkhead Box O3), resulting in tumour suppression." (PMID 38693857, 2024). "Strong evidence exists that FOXO3, which acts as a tumor inhibitor, regulates cell cycle arrest, cell death, and DNA damage repair." (PMID 37976368, 2024). "In cancer, FOXO3 can inhibit tumor growth and metastasis by regulating the expression of genes responsible for cell proliferation, angiogenesis, and invasion." (PMID 39334758, 2024). "To further investigate this relationship, we employed siRNA or TIC10, targeting Foxo3, to assess its impact on the anti-tumor effect of CAPE." (PMID 39729481, 2024). "This downregulation of FOXO3, a tumor suppressor with roles in cell cycle arrest and apoptosis, contributes to the unchecked proliferation and survival of malignant prostate cells." (PMID 39796040, 2024). "For instance, in an orthotopic liver tumor model, the ablation of the METTL3/FOXO3 axis was reported to weaken the antitumor efficacy of sorafenib, leading to enhanced tumor autophagy, angiogenesis, and a subsequent acceleration of tumor growth." (PMID 38566136, 2024). "Specifically, FOXO3 expression in normal tissues was significantly higher than that in tumor tissues (P < 0.05)." (PMID 37976368, 2024). "The interaction of MDM2 and circFOXO3 also prevents MDM2 from binding to FOXO3, another tumor suppressor, leading to increased FOXO3 levels and tumor apoptosis." (PMID 39337606, 2024).
tumor (continued). "The COAD dataset retrieved from the TCGA database was analyzed, and the expression data of "GPX4" and "FoxO3" in tumor patients were extracted." (PMID 39668836, 2024). "In contrast to FOXM1, FOXO3 is regarded as a tumor suppressor and the overexpression of FOXO3 can inhibit the proliferation, tumorigenic potential and invasiveness of various cancer cells." (PMID 38725864, 2024). "FoxO3 can lead to autophagosome formation by increasing the activity of glutamine synthase and contribute to FoxO3 inhibiting the proliferation of tumor cells." (PMID 36994237, 2023). "Inhibiting miR-155 induced cell death and reduced proliferation, which coincided with higher expression of FOXO3, suggesting FOXO3 possesses tumour suppressive qualities in DLBCL." (PMID 37275916, 2023). "While other of them are lowly expressed in tumor tissues, which can continuously activate their host genes and inhibit the malignant phenotype of tumors as tumor suppressors, such as circ-Foxo3, circ-ITCH and circ-FBXW7." (PMID 37060016, 2023). "The down-regulation of transcription factor FOXO3 has been shown in animal models to promote tumourigensis and tumour proliferation." (PMID 37293994, 2023). "The regulation of acetylated proteins such as CREB binding protein (CBP), ALDH1A1, α-tubulin, cortactin and Forkhead Box O3 (FOXO3) show tumor-suppressing effects in BC." (PMID 37189694, 2023). "This regulatory phenotype is acquired due to the presence of immunosuppressive mediators, such as the expression of the transcription factor Forkhead box O3 (Foxo3) within the tumor." (PMID 37781382, 2023). "In another report, in a mouse ovarian tumor model, metformin suppressed STAT3 and c-Myc through activation of FOXO3 tumor suppressor protein in the tumor and subsequently downregulates PD-L1 expression, which leads to activation of CD8+ TILs." (PMID 37686159, 2023). "Circular Foxo3 sponges miRNA and MDM2, which represses parent Foxo3; thus, the repression of circular RNA Foxo3 results in the repression of Foxo3 mRNA, ultimately reducing the life span of tumor-bearing mice." (PMID 37895357, 2023). "This suggests BCP-ALL promotes cell growth and survival by means of bypassing the expression of tumour suppressive components such as FOXO3." (PMID 37275916, 2023). "Studies suggest a tumour suppressive role for FOXO3, as pharmacological inhibition of PI3K-AKT-mTOR signalling resulted in dephosphorylation and activation of FOXO3 leading to a reduction in MCL cell survival and proliferation." (PMID 37275916, 2023). "d) Role of FOXO3 in modulating oxidative stress is complicated and is highly dependent on the amount of available ROS produced by other regulators in tumor cells." (PMID 37821870, 2023). "FOXO3 was identified as a tumor suppressor gene with downregulation of circ-FOXO3 following cancer initiation due to increased Akt activity or loss of PTEN." (PMID 37243750, 2023). "Elevated ROS levels can shift the interaction of β-catenin from transcription factor 4 (TCF4) to forkhead box O3 (FOXO3a) and thus prevents tumorigenicity in vitro and tumor formation in vivo." (PMID 38017510, 2023). "Immunohistochemical analysis of residual KPC tumours showed re‐organisation of tumour stromal architecture, suppression of proliferation and nuclear retention of tumour suppressors, such as Forkhead Box O3a (FOXO3a)." (PMID 38131168, 2023).
tumor (continued). "While investigating regulatory events upstream of BTC, we found FOXO3, a transcription factor with well‐established function of tumor suppression, as a probable mediator of inhibitory effects of omega 3 fatty acids on BTC." (PMID 37859621, 2023). "Functionally, FOXO3 is a TF that regulates multiple pathways including tumor angiogenesis, and PI3K-AKT signaling pathway." (PMID 36720864, 2023). "RORγt+ Tregs are also required to suppress Foxo3 in tumor-infiltrating DCs, leading to the establishment of a IL-6 rich, pro-tumor microenvironment." (PMID 37197653, 2023). "As the association between the transcriptional activation of a major tumor suppressor gene, FoxO3, and ATP1A1 signaling has been established, we proceed to explore the association of the ATP1A1 and the pro-autophagic gene, FoxO1 in MASH-HCC." (PMID 37830582, 2023). "Metformin mediates dual blocking of STAT3-PDL-1 and c-Myc-PDL1 pathways in tumor through upregulation of FOXO3, and therefore, it enhances CD8+ TILs activation." (PMID 37686159, 2023). "In a mouse model, it was demonstrated that circ-Foxo3 transfected MDA-MB-231 tumor growth considerably decreased as compared to the control." (PMID 37400900, 2023). "Similar to FOXO1, FOXO3 (also known as FOXO3a) is generally considered a tumor suppressor in different cancers, and its sub-cellular localization was shown to be crucial for its activity." (PMID 37821870, 2023). "Expression of constitutively active FOXO3 increased levels of cell death whereas a reduction in FOXO3 expression increased cell survival, providing evidence for FOXO3 playing a tumour suppressor role in CLL cells." (PMID 37275916, 2023). "The authors concluded that FOXO3 promotes tumor growth under hypoxic conditions and promotes tumor angiogenesis in advanced-stage NB tumors." (PMID 37834193, 2023). "The key variations include loss of PTEN, copy gain of HSP90AA1, and mutations in FOXO3 or BCL2, all of which are well established to contribute to tumor cell growth and survival." (PMID 36831263, 2023). "Exosome-mediated lncRNA LBX1-AS1 sponged miR-182-5p to upregulate FOXO3, leading to inhibited cell proliferation and migration, which also restrained tumor growth in vivo in OSCC." (PMID 37476905, 2023). "FOXO3 has been reported to regulate energy metabolism in response to stress signals in haematopoietic and tumour cells." (PMID 37114094, 2023). "FOXO1 and FOXO3 have been found to be highly phosphorylated and inactivated, suggesting tumour suppressive functions for FOXOs in MM." (PMID 37275916, 2023). "Circ-Foxo3 expression was significantly downregulated in spheroid-forming tumor cells, according to our data." (PMID 37400900, 2023). "In tumor cells, FOXO3 protein binds to circFOXO3, inhibiting the binding of FOXO3 to E3 ubiquitin-protein ligase MDM2 (MDM2), and promoting the enrichment of FOXO3 protein, thereby inducing tumor cell apoptosis." (PMID 36344492, 2022). "have reported that B and T cells infiltrate the tumor and the surrounding connective tissue in breast cancer and express circ-Foxo3." (PMID 35464462, 2022). "uncovers a critical function for METTL3-mediated m6A modification in the hypoxic tumor microenvironment and identifies FOXO3 as an important target of m6A modification in the resistance of HCC to sorafenib therapy." (PMID 35440025, 2022). "It indicates a host immune response to tumor xenografts, with circ-Foxo3 playing a tumor-suppressive role." (PMID 35464462, 2022). "Treg growth is induced by reduced mTOR signaling via FOXO3 expression; Tregs with the forkhead box 3+ (FOXO3+) gene play a crucial role in tumor immunity by suppressing effector T cells." (PMID 36428613, 2022). "The latest literature has documented that circ-Foxo3 has binding sites for multiple miRNAs and can act as a ceRNA to inhibit or promote tumor growth." (PMID 36139427, 2022).
tumor (continued). "Most studies have demonstrated that FOXO3 acts as a tumor suppressor, and emerging evidence also indicates that FOXO3 plays a promotive effect in some cancers." (PMID 34795388, 2022). "FOXO3 is a transcription factor with key role in cell cycle, apoptosis, aging regulation, and tumor suppression." (PMID 34850406, 2022). "Of these, five candidate tumor-suppressor genes, including FOXO3, HACE1, PRDM1, ATG5, and AIM1, were identified in the minimal region in del 6q21." (PMID 35054466, 2022). "Increased FOXO3 nuclearlocalization is involved in neuroblastomachemoresistance and tumor angiogenesis." (PMID 36188303, 2022). "A total of 31 of 33 tumor types showed a positive correlation between the CNV of FOXO3 and its mRNA level." (PMID 36555288, 2022). "Although circ-Foxo3 is minimally expressed in tumor specimens, the expression of circ-Foxo3 gradually increases during cancer cell apoptosis." (PMID 36338714, 2022). "Mechanistically, JWA regulates glycolysis and mitochondrial oxidative phosphorylation through the AMPK (AMP-activated protein kinase)/FOXO3 (Forkhead box O3) pathway to participate in energy metabolism and inhibit tumor metastasis." (PMID 36230577, 2022). "As a competing endogenous RNA, LBX1-AS1 stimulates Mφs by acting on miR-182-5p and fork head box protein O3 (FOXO3), causing Mφs polarization and activating Mφs to regulate the development of tumor cells." (PMID 35145526, 2022). "The tumor-suppressive function of FOXO3 and PRDM1 in NK cell neoplasms was proven by genomic and functional analyses." (PMID 35054466, 2022). "Expression of the RNA for FoXO1, FoXO3, and Atrogin-1, key genes in skeletal muscle proteolysis, were elevated along with the tumor development." (PMID 35847939, 2022). "Transcription factor forkhead Box O3 (FOXO3) is related to various tumor development process such as metastasis and angiogenesis." (PMID 35207737, 2022). "The very well controlled intrinsic modes of NK cell development, differentiation, and maturation by FOXO1 and FOXO3 revealed in our study can drive future efforts to develop anti-tumor and anti-viral immunotherapies targeting FOXO proteins." (PMID 35757763, 2022). "Specifically, FoXO1, FoXO3, and Atrogin-1 mRNA levels and protein Murf-1 and Atrogin-1 were markedly increased in tumor-bearing mice compared to control." (PMID 35847939, 2022). "In particular, exosome-borne miR-155 enhances new vessels formation in vitro through inhibition of Forkhead box O3 (FOXO3a) expression, which is also known to sustain tumor progression." (PMID 35454874, 2022). "SUMOylation positively regulates FOXK2 transcriptional activity and has a role in mediating the cytotoxic response to paclitaxel through the tumour suppressor FOXO3." (PMID 36172141, 2022). "FoxO3 has been implicated as a tumor suppressor in HCC carcinogenesis and PTEN-mediated tumor suppression is driven by the repression of survivin gene transcription via the direct binding of FOXO3 to the survivin promoter." (PMID 35806364, 2022). "Previous study reported that FoxO1 and FoxO3 were two major participants involved in regulating tumor cell survival under Trastuzumab treatment, therefore, we evaluated the expression states of FoxO1, FoxO3, FoxO4 and FoxO6." (PMID 35835735, 2022). "Du et al12 reported the application of gold nanoparticles to deliver circ‐Foxo3 in mice to inhibit tumour progression." (PMID 33277969, 2022). "As one of the well-studied circRNAs in cancers, circRNA forkhead box O3 (Foxo3) acts as either an anti-tumor or pro-tumor regulator in various cancer types." (PMID 34555810, 2021). "RNAscope in situ hybridization detected Foxo3 mRNA in normal epithelial cells of the wild-type mouse stomach and Gan mouse tumor cells." (PMID 33795838, 2021). "Meanwhile, the inhibitory role of LINC00472 in tumorigenesis was validated in vivo, and the LINC00472‐mediated miR‐23a‐3p/FOXO3/BID axis was also demonstrated in the nude mouse tumour formation model." (PMID 34363438, 2021).
tumor (continued). "Accumulating studies have shown that circ-Foxo3, as a powerful tumor suppressor that sponges certain miRNAs, is downregulated in many cancers." (PMID 33833780, 2021). "Using a second set of GBM tumor samples (n = 20, samples frozen at –80°C), we used dual-label immunofluorescence to evaluate the expression of FOXO3 and SOX2 within the same tumor region and cell." (PMID 36303712, 2021). "Akt is a well-known oncogenic kinase that obstructs the tumor suppressive function of the FOXO3 transcriptional factor by promoting proteasome-mediated protein ubiquitination following phosphorylation." (PMID 34745413, 2021). "Here, we found that even with increased IL-6 and FoxO3 expression in both tumour-bearing groups, leucine supplementation blunted the expression of key catabolic related proteins, MuRF-1, and 20S." (PMID 34943780, 2021). "SIRT1 and CUL4B were found to be significantly upregulated in tumors, with their level of expression positively correlated with tumor histological grades, while FOXO3 expression was negatively correlated with tumor histological grades." (PMID 34163012, 2021). "Based on the results from 50 healthy liver samples and 371 HCC patients, FOXO3 is significantly greater expressed in tumor samples." (PMID 34769197, 2021). "They demonstrated that the inhibitory effects of Foxo3, Foxo3P, and circ-Foxo3 on tumor growth were due to decreased blood vessel formation and nutrition supply." (PMID 34400888, 2021). "They presented that the ectopic expression of endogenous circ-Foxo3 led to apoptosis and retardation of tumor progression, while silencing circ-Foxo3 had the opposite effect." (PMID 33833780, 2021). "The low expression of has_circ_0001368 can promote tumor growth, and it plays a tumor suppressor effect in GC through the miR-6506-5p/FOXO3 axis." (PMID 34356052, 2021). "Many of the genes regulated by FOXO3 carry out anti-proliferative (cell cycle arrest) and pro-apoptotic functions (control of cell death), thus categorizing FOXO3 as a tumor suppressor." (PMID 34201262, 2021). "Here, we use a library of peptides from diverse prokaryal genomes to screen MMIs promoting the nuclear relocalization of Forkhead Box O3 (FOXO3a), a tumor suppressor more frequently inactivated by post-translational modification than mutation." (PMID 34111400, 2021). "Yang and co-workers identified an inhibitory role of forkhead DNA-binding protein-Foxo3 circRNA on tumor growth and angiogenesis." (PMID 33763348, 2021). "The forkhead box O3a protein (FoxO3a) has been reported to regulate tumour invasion and migration, but little is known about the molecular mechanism or its role in trophoblast invasion and migration into the uterus." (PMID 33811439, 2021). "Intriguingly, our observation that Foxo3 was upregulated in OC is inconsistent with previous reports that Foxo3 acts as an anti-tumor factor in cancers." (PMID 34555810, 2021). "Contrary roles of FOXO3 have been found in different cancer types, acting as a tumor suppressor but also favoring tumor progression under certain conditions." (PMID 34769197, 2021). "FOXO3, as a tumor inhibitor, is a transcription factor with multiple biological functions, including antioxidant response, longevity, and cell cycle control." (PMID 34795217, 2021). "In summary, circ-Foxo3, as a widely accepted tumor suppressor in UC, is a potential therapeutic target and prognostic biomarker for UC patients." (PMID 33833780, 2021). "Forkhead transcription factors FOXO1 (Forkhead box O1) and FOXO3a (Forkhead box O3a) play a critical role in tumor suppression by inducing growth arrest and apoptosis." (PMID 34068643, 2021). "Contrary to its paralog FOXO1, the implication of FOXO3, a well-established tumor suppressor with regular overlap and functional redundancy, has not received particular attention in PAH." (PMID 33805714, 2021).